S100A9 (S100 calcium binding protein A9)
Diseases named in the same sentence as S100A9 in open-access papers (continued):
Sharing a sentence is not in itself a finding about the gene and the disease.
tumor (continued). "In summary, S100A9 exerted pro-tumor effects through not only autocrine effect on cancer cells but also paracrine effect on stromal cells, including inflammation promotion and angiogenic activation." (PMID 26315114, 2015). "S100a8 was elevated in both 67NR/4T1.2 and EO771/EO771.LMB tumour comparisons, although differential expression of S100a9 was found only in 4T1.2/67NR." (PMID 25633981, 2015). "Compared with a number of other members of the S100 protein family, the expression levels of S100A8 and S100A9 in several types of tumor were significantly different to those in normal samples, but rarely in RCC." (PMID 25673070, 2015). "Tasquinimod, an orally active quinoline-3-carboxamide, binds with high affinity to HDAC4 and S100A9 in cancer and infiltrating host cells within compromised tumor microenvironment inhibiting adaptive survival pathways needed for an angiogenic response." (PMID 25193858, 2014). "S100A9 knockout (KO) mice showed a decrease in immature myeloid cells and a potent anti-tumor immune response." (PMID 25538893, 2014). "MDSCs in turn express and secrete S100A9 and can, under hypoxia, differentiate via HIF-1α dependent transcription into tumor- associated macrophages which secrete angiogenic factors such as VEGF, FGF, TNF-α, and TGF-β." (PMID 25193858, 2014). "High levels of S100A9 have been found in the microenvironment of several forms of tumours, and a high expression level has been correlated with poor tumour differentiation." (PMID 24162378, 2014). "For instance, S100A9 expressed by myeloid cells and tumour cells in the tumour microenvironment is important for the accumulation and activation of regulatory myeloid cells (e.g. MDSC and TAM)." (PMID 24162378, 2014). "Growing evidence indicates that tasquinimod targets the myeloid cell compartment and modulates local tumour immunity by binding to the calcium-binding protein S100A9." (PMID 24162378, 2014). "In investigating tumor-stromal interactions, particular attention should be paid to the inflammatory proteins S100A8 and S100A9, which are encoded by genes clustered on chromosome 1q21." (PMID 24670043, 2014). "We have previously also shown that the inhibition of S100A9 and TLR4 expression influenced EL4 tumor growth, and that the inhibition of S100A9 interactions in vivo using Q compounds mimicked this effect." (PMID 23667563, 2013). "In cancer patients, accumulation of myeloid-derived suppressor cells (MDSC), which are known to impair anti-tumour immunity (notably by decreasing cytotoxic function of NK cells), are regulated by S100A9 protein." (PMID 24156302, 2013). "In this paper we show that it is possible to define a novel small molecule compound (OX) that has anti-tumor effect in vivo by selecting for binding to S100A9 and inhibition of its interaction with RAGE." (PMID 23667563, 2013). "We have previously reported that glyphosate potentially causes tumor promotion in two-stage mouse skin carcinogenesis model, and S100A6, S100A9 (Ca2+-regulating proteins), SOD 1 (oxidative stress-related protein) are associated with this tumor promotion." (PMID 24073338, 2013). "Lastly, S100A8 and S100A9 also play a role in cell proliferation and metastasis of primary tumours into the lung." (PMID 26464846, 2013). "The differential expression of S100A4 and S100A9 in both healthy animals and in animals with ongoing inflammatory disease or tumor burden was striking." (PMID 23667563, 2013). "The positive rates of S100A8 and S100A9 in tumor cells were 54.8% and 69.1% in the CRC tissues, compared to 7.1% and 16.7% in the matching distal normal tissues respectively (p<0.001)." (PMID 23637971, 2013). "Among the complex network of cytokines and inflammatory molecules at the tumor stroma interface that fosters MDSCs, the S100A8 and S100A9 proteins, expressed by both stromal and tumor cells, appear relevant in the PDAC setting." (PMID 23359812, 2013).
tumor (continued). "The expression pattern of S100A6 and S100A9 expressions was found to be considerably enhanced in some tumor tissues like hepatocellular carcinoma, lung cancer, colorectal cancer, and melanoma." (PMID 24073338, 2013). "In tumorigenesis, MDSCs are attracted from bone marrow to peripheral blood by inflammatory cytokines (e.g., interleukin-1β, interleukin-6, prostaglandin E2), chemokines, tumour-derived growth factors, and myeloid-related proteins such as S100A9 and S100A8." (PMID 26464846, 2013). "Previously, we have reported that glyphosate potentially causes tumor promotion in mouse skin carcinogenesis and S100A6, S100A9, and SOD 1 are associated with this tumor promotion." (PMID 24073338, 2013). "S100A4 and S100A9 proteins have been described as playing roles in the control of tumor growth and metastasis." (PMID 23667563, 2013). "S100A8 and S100A9 not only promote the recruitment of CD11b+ myeloid cells but also act as chemoattractants which draw tumour cells to premetastatic sites in the lungs." (PMID 26464846, 2013). "There was a modest increase of S100A9 mRNA in both splenic populations (CD11b+Ly6C+G+ and CD11b+Ly6C+G-/C++G-) in EL-4 tumor bearing animals." (PMID 23234398, 2012). "Next, we quantified the number of S100A8-positive inflammatory cells in each tumor tissue for S100A9." (PMID 22838504, 2012). "We next analyzed the effect of a tumor challenge on the CD11b+ cell populations and their respective S100A9 expression." (PMID 23234398, 2012). "Having investigated the effect of a tumor challenge on the CD11b+Gr1+ cell distribution and S100A9 expression we decided to compare this to what was observed in chronic inflammation." (PMID 23234398, 2012). "S100A8/S100A9 expression is increased in patients with various tumours, being involved in invasion and migration processes." (PMID 22673103, 2012). "Having established that S100A9 expression had an impact on tumor growth we proceeded to perform an immunoflourescence analysis of tumors from TRAMP mice." (PMID 22470535, 2012). "We propose that S100A8 and S100A9 proteins from either infiltrating inflammatory cells or tumor cells play an important role in the interplay among inflammation, angiogenesis, and tumorigenesis." (PMID 22685372, 2012). "S100A8 and S100A9 play critical role in tumor biology and their elevated levels were found in numerous tumors including gastric, colon, pancreatic, bladder, ovarian, thyroid, breast, skin and prostate cancers." (PMID 22489132, 2012). "The number of S100A9 positive cells in the tumor stroma correlated to the number of tumor infiltrating CD68 positive macrophages." (PMID 22470535, 2012). "Immune mediators such as S100A9 can play both anti-tumor and tumor promoting roles depending on the cancer types." (PMID 22838504, 2012). "We also observed a significant reduction of tumor weight in S100A9−/− animals, as previously published." (PMID 22470535, 2012). "We conclude from these experiments that the distribution of CD11b+ cell subpopulations, as well as their S100A9 expression, appears to be dynamic and change both depending on tumor challenge and on tissue location." (PMID 23234398, 2012). "In human GBM primary tumor parenchyma, S100A8 and S100A9 have been identified with higher levels of S100A9 noted in the tumor regrowth parenchyma of patients that received primary resection plus irradiation compared to primary resection alone." (PMID 22251275, 2012). "In the spleen, the most pronounced S100A9 expression was in the Ly6C+G+ population, similarly as to what was observed in tumor bearing animals." (PMID 23234398, 2012). "In a recent publication, we investigated the impact of S100A9- and TLR-4 deficiency on tumor growth in the TRAMP prostate cancer model." (PMID 23234398, 2012). "Correlation between S100A9 cell count and other clinical features such as sex, age, tumor location, liver metastasis (M stage), vascular invasion and differentiation were not statistically significant (all P > 0.05)." (PMID 22838504, 2012).
tumor (continued). "By using immunostaining the expression of S100A8 and S100A9 are shown in the tumor cells such as U251MG glioma, A-431 epidermoid carcinoma and U-2 OS human osteosarcoma cell lines." (PMID 22489132, 2012). "It has been suggested that tumor cells of glandular origin can express S100A9 when they are poor differentiated or under pathological stress conditions." (PMID 22838504, 2012). "Several other studies performed using the DMH or azoxymethane (AOM)-induced CRC model also found high expression levels of S100a9 and Defa in tumor tissues." (PMID 21857934, 2011). "Nevertheless, further studies need to be conducted to validate S100-A9 as a marker for tumor infiltration or as a possible candidate with prognostic predictions concerning tumor development." (PMID 21760917, 2011). "Increased S100-A9 levels were detected in various human cancers, presenting abundant expression in neoplastic tumor cells as well as infiltrating immune cells." (PMID 21760917, 2011). "S100-A9 was found in inflammatory cells in blood vessels as well as in the interstitium indicating tumor infiltration." (PMID 21760917, 2011). "Recently, the increased S100A8 and S100A9 levels were also detected in various human cancers, presenting abundant expression in neoplastic tumor cells as well as infiltrating immune cells." (PMID 20497537, 2010). "This scheme reiterates the ability of S100A8 and S100A9 to act as ligands for Ager (advanced glycation end-product receptor), which mediates acute and chronic inflammation, tumor development, and metastasis." (PMID 21318167, 2010). "Other proteins that were highly expressed in the tumor tissue were S100 calcium binding protein A9 and Peptidylprolylisomerase A." (PMID 19491504, 2009). "Upregulation of S100A8 and S100A9 in premetastatic lung tissue provide a niche for migration of tumor cells." (PMID 19292913, 2009). "Furthermore, the proportion of RMC tumor cells expressing the myeloid lineage marker S100A9 and the cell proliferation marker MKI67 was significantly higher following ICT treatment." (PMID 41290625, 2025). "Furthermore, IL-6-mediated STAT3 activation induces the expression of S100A9, a factor that promotes tumor invasion and metastasis." (PMID 41409248, 2025). "S100a9, a member of the S100 proteins superfamily and a calcium‐binding protein also known as myeloid‐related protein 14 (MRP‐14), exhibits elevated expression under various stress conditions in cell types including tumor cells, endothelial cells, microglia, and neurons." (PMID 40904186, 2025). "In addition, S100A9 expression is augmented in many solid tumors, promoting tumor growth, metastasis, drug resistance, and immune suppression." (PMID 41173834, 2025). "Tumour samples from Sudan exhibited altered expression of S100A7, S100A9, glutathione transferase, lactoglobulin, and stratifin, while normal controls compared to tumours showed changes in ferritin light subunit, fast skeletal myosin, fibrinogen, and a hypothetical protein." (PMID 39982954, 2025). "Furthermore, mechanistic insights into the S100A9-mediated signaling revealed that S100A9 mediates its tumor-intrinsic effects by binding to the RAGE receptor in an autocrine loop." (PMID 41173834, 2025). "When S100A8 and S100A9 are secreted into the extracellular space, they act as pro-inflammatory danger signals and have been shown to play a pivotal role in tumorigenesis by influencing inflammation, proliferation, invasion, and metastasis of tumor cells." (PMID 40725477, 2025). "While there is substantial evidence supporting the involvement of S100A9 in the tumor immune microenvironment and immune evasion, the roles of CCL27, ID4 and LRP4, genes that also showed strong correlations with infiltrating immune cells, remain inadequately explored." (PMID 40296873, 2025).
tumor (continued). "Furthermore, the in vivo studies using SCLC xenograft and syngeneic murine models demonstrate that downregulating S100A9 significantly reduces tumor growth, accompanied by reduced expression of proliferative and angiogenic markers." (PMID 41173834, 2025). "In vitro experiments revealed that Bv8, S100A8 and S100A9 could all stimulate tumor cell migration, indicating a direct role for these molecules in both neutrophil and tumor cell migration." (PMID 39653768, 2025). "Interestingly, downregulation of S100A9 expression in cSCC has been shown to inhibit tumor proliferation and migration." (PMID 40296873, 2025). "HMGB1 and S100A9, as immune-related DAMPs, may increase transiently after immune checkpoint blockade or chemotherapy due to treatment-induced tumor cell death and immune activation." (PMID 41009692, 2025). "It has been reported that S100A8 and S100A9 levels may be a potential prognosticator of DFS in tumor patients; a high percentage of S100A8 and S100A9 means a low DFS." (PMID 41164825, 2025). "Furthermore, decreased tumor cell proliferation (Ki-67 expression) and tumor neovascularization (CD31 expression) were observed in S100A9-downregulated tumors compared to controls." (PMID 41173834, 2025). "Responses to ICB have been associated with TIICs, an increase in tumor-infiltrating PD-1hiCD8+T cells, LAG3+CD8+T cells and monocytes/macrophages in tumor as well as S100A9+CD14+monocytes in the peripheral blood of patients exhibiting suboptimal responses to anti-PD-1 therapy." (PMID 41438767, 2025). "Furthermore, S100A8 and S100A9 were shown to be involved in neutrophil and tumor cell motility as well as tumor cell survival, making them interesting targets for preventing metastasis." (PMID 39653768, 2025). "Notably, inhibiting S100A9 significantly attenuates the tumor-promoting effects of these exosomes, reducing tumor growth by 51%." (PMID 41357241, 2025). "Future studies exploring the role of S100A9 as well as other alarmins in cancer is of great importance for the development of new therapeutics aimed at tuning the anti-tumor immune response and for understanding the resistance mechanisms to current treatments such as checkpoint inhibition." (PMID 39497822, 2024). "Furthermore, we assessed the relative mRNA levels of S100A8, S100A9, Nos2, and Arg1 in the tumor tissues." (PMID 38952044, 2024). "Moreover, we identified the Mono_S100A9 signature as a predictive biomarker, indicative of reduced efficacy in immunotherapy and decreased survival benefits across various tumor types." (PMID 38454445, 2024). "In this scenario, the components of the ECM in the tumor stroma can establish crosstalk with secreted proteins that regulate inflammation and innate immunity, as suggested by the interaction among basigin, Gal-3, and S100A9." (PMID 39195201, 2024). "Thus, 10 μM was chosen as a non-toxic concentration to study the effects of HIS on the IL-6/STAT3/S100A9 pathway, excluding direct tumor growth interference." (PMID 39720595, 2024). "Increased levels of S100A9 in the tumor resulted in significantly reduced tumor growth." (PMID 39497822, 2024). "Interestingly, the transcriptomic analysis showed that the spheroid co-culturing, compared to separate mono-cultures of HT-29 and fibroblasts, induced upregulation of INHBA, SerpinA1 and S100A9, which are well-known players in tumor biology." (PMID 39011470, 2024). "To further study the function of S100A9 in GBM, we conducted GO and KEGG enrichment analysis on the DEGs screened from high- and low-expression groups of S100A9 and found that S100A9 participated in a variety of pathways and biological processes related to tumor progression and immune regulation." (PMID 39137310, 2024). "In addition, due to the fact that S100A9 protein not only exists in cancer cells but can also be secreted into the extracellular environment, its potential as a promising biomarker for tumor diagnosis or prognosis prediction has received widespread attention." (PMID 39137310, 2024).
tumor (continued). "Additionally, our findings shed light on the potential involvement of S100A9-positive macrophages in fostering tumor immune evasion, offering valuable perspectives on the immunoregulatory processes operative in GBM." (PMID 39136841, 2024). "In addition, a distinct S100A9+ tumor cell subtype was identified in both primary and metastatic sites, which is strongly associated with poor prognosis." (PMID 39605915, 2024). "To investigate if we could reverse the Paquinimod effect and improve the anti-tumor immune responses, we tested intratumoral injection of recombinant S100A9 protein." (PMID 39497822, 2024). "In contrast to the Paquinimod treatment, S100A9 injection did not cause any clear changes to tumor immune cell infiltration." (PMID 39497822, 2024). "Meanwhile, S100A8/S100A9 from BC cells binds to receptor for advanced glycation end products on MDSCs and can activate the mitogen-activated protein kinase and nuclear factor kappa-B (NF-κB) signaling pathways in tumor cells to stimulate tumor invasion." (PMID 38404689, 2024). "Our findings suggest that S100A8/S100A9 act as tumor‐promoting inflammatory cytokines and may serve as prognostic indicators for OLK." (PMID 38962427, 2024). "In GBM, the expression of S100A9 in myelogenous suppressor cells was significantly increased, and this change was observed in a variety of tumors, which was believed to induce changes in tumor immune microenvironment leading to immunosuppression." (PMID 39137310, 2024). "In cancer however, S100A9 has received most attention for its role in tumor-promoting inflammation, and in the development and recruitment of myeloid derived suppressor cells (MDSCs), which limit beneficial anti-tumor immunity." (PMID 39497822, 2024). "Thus, it seems that there is a critical time-window during early tumor growth, for a beneficial effect of S100A9 on anti-tumor control, which is blocked by Paquinimod." (PMID 39497822, 2024). "While EVs-isolated tumour markers are often sought among molecules expressed by cancer cells, we chose to explore whether this is the case for S100A9 protein present in EVs isolated from plasma of CRC patients with rHGP-type of liver metastasis." (PMID 39516397, 2023). "Within the tumor microenvironment, S100A9 is highly expressed by various myeloid cell populations (e.g., myeloid-derived suppressor cells) and plays a critical role in the formation of an immunosuppressive niche which favors tumor growth and drug resistance." (PMID 38110349, 2023). "Interestingly, besides its clear single agent anti-tumor effect, our data also demonstrated the therapeutic potential of S100A9-targeting therapies in combination with standard-of-care agent venetoclax." (PMID 38110349, 2023). "The expression of MDSC marker genes such as Itgam, S100a9, and Clec4e, and tumor proliferation-associated genes, Ccnd1 (Cyclin D1) and Myc (c-Myc), was enhanced after PGE2-administration, indicating that MDSC expansion and tumor growth are promoted by PGE2." (PMID 36932082, 2023). "Therefore, in this study we aimed to explore the role of S100a9 in tumor escape and to identify its potential mechanisms." (PMID 36810783, 2023). "M-MDSCs can further differentiate into tumour-associated macrophages (TAMs) which have an immunosuppressive M2 phenotype that secrete IL-10, express PD-1 and contribute to tumour angiogenesis, and appears to depend on S100A9 expression and signalling acting via C/EBPbeta." (PMID 37033972, 2023). "The secretion of S100A8 and S100A9 by M-MDSCs might provide positive autocrine feedback loop that ensures the maintenance of functionally suppressive MDSCs within an inflammatory tumor environment." (PMID 38304256, 2023). "Future studies will be necessary to define the functional significance and underlying mechanisms of other tumor supportive cytokines/chemokines (i.e., IL1A/B, LIF, G/M-CSF and CXCL2/3) and inflammatory proteins (i.e., S100P and S100A9) in mediating XIST regulation of tumor growth and CSC activity." (PMID 36922677, 2023).